MTOR (mechanistic target of rapamycin kinase)
Diseases named in the same sentence as MTOR in open-access papers (continued):
Sharing a sentence is not in itself a finding about the gene and the disease.
cancer (continued). "We confirmed that COTI-2 treatment reduced phosphorylated-AKT and -caspase-9 in SHP-77 cells suggesting a role for it negatively modulating the PI3K/AKT/mTOR pathway in cancer cells." (PMID 27150056, 2016). "In a follow-up study, we assessed the impact of a more frequent dose of CDD866 and everolimus, a new generation, less cytotoxic, molecular-targeted agent, which inhibits the mammalian target of rapamycin (mTOR), on cancer cachexia." (PMID 27462398, 2016). "PGRN-activated mTOR was confirmed in other cancer cells, including A549, MCF-7 and SKOV-3 cell lines." (PMID 27517315, 2016). "An attractive molecular target for novel anti-cancer therapies is the phosphatidylinositol 3-kinase (PI3K)/Akt/mammalian target of rapamycin (mTOR) pathway which is commonly deregulated in many types of cancer." (PMID 27494886, 2016). "Given that pan-mTOR inhibitors are already undergoing clinical trials for cancer therapy, one can envision their fast application for prevention of age-related diseases by slowing down aging." (PMID 28077803, 2016). "Stimulation of the PI3K/Akt/mTOR pathway, which controls cell proliferation and growth, is often observed in cancer cell." (PMID 26956874, 2016). "Although additional studies are required to determine their specific role in the clinical setting, mTOR inhibitors represent a promising therapeutic option for the treatment of cancer." (PMID 27920721, 2016). "The eIF4E-binding proteins (4E-BPs) are critical repressors of cap-dependent translation via mTOR, a pathway frequently hyperactivated in cancer." (PMID 27319316, 2016). "While the role of the PI3K-Akt-mTOR axis in cancer pathogenesis is well-established, its involvement in the regulation of CSCs has only become more evident in the last decade." (PMID 27826244, 2016). "In the PI3K/AKT/mTOR pathway, the set of hub genes in the estimated differential networks is significantly enriched with drug resistance-related genes and cancer-related genes." (PMID 27677586, 2016). "In contrast, a recent study on cancer cachexia in mice observed an increase in Akt activation, while mTOR signaling and FoxO activity were suppressed." (PMID 26856534, 2016). "In this review, we discuss the role of tumor microenvironment and macrophages in cancer; M1 and M2 differentiation and the role of mTOR pathway; and M1 and M2 macrophages as possible tumor markers." (PMID 28074082, 2016). "Inhibition of the mechanistic target of rapamycin (mTOR) is a promising treatment strategy for several cancer types." (PMID 27223077, 2016). "mTOR inhibitors are approved to treat some cancers, with presumed effects on cancer cell proliferation or metabolism, and with many new mTOR inhibitors in development or in clinical trials." (PMID 26315673, 2015). "There is strong interest in targeting mTOR for cancer therapy, in part based on genetic studies showing selective effects on tumor cells following mTOR inactivation." (PMID 25576920, 2015). "We genotyped five potentially functional PIK3R1 and mTOR SNPs in 1116 esophageal squamous cell cancer (ESCC) patients and 1117 cancer-free controls to assess their associations with ESCC risk." (PMID 25654238, 2015). "In particular, the activation of AMPK negatively regulates the cancer cell growth through downstream mTOR signaling pathways." (PMID 26656173, 2015). "There are results also demonstrate that combination of CK2 inhibitor CX-4945 with erlotinib (EGFR tyrosine kinase inhibitor) results in synergistic killing of cancer cells by attenuating the PI3K-Akt-mTOR pathway." (PMID 26172393, 2015). "The AMPK/mTOR signaling pathway has been widely studied in metabolic disorders and an increasing number of studies also suggest a potential role in cancer cell biology." (PMID 25909163, 2015). "In cancer, mTOR is frequently hyperactivated and is a clinically validated target for drug development." (PMID 28943624, 2015).
cancer (continued). "Given that a number of downstream mTOR effectors regulating angiogenesis, metabolism, and cell growth have been found to be deregulated in cancers, various targeted therapies such as temsirolimus and everolimus have been developed to hinder mTOR signaling." (PMID 25734007, 2015). "The PI3K/Akt/mTOR pathway is a critical signaling pathway that negatively regulates autophagy and that promotes cancer progression." (PMID 25743109, 2015). "In many types of cancers, mTOR is aberrantly activated because of dysregulation of mTOR regulators or aberrant upstream signaling such as PI3K/AKT activation and PTEN loss." (PMID 26460955, 2015). "It is anchored in the ER and Golgi apparatus, instead of lysosomes for Rag GTPases, which is consistent with that mTOR is found in these organelles in many different types of cancer cells." (PMID 26308575, 2015). "The mechanistic target of rapamycin (mTOR) has received considerable attention as a potential target for cancer chemotherapy." (PMID 26490657, 2015). "We therefore conclude that, through the post-transcriptional regulation of genes such as mTOR within cancer pathways, LARP1 contributes to cancer progression." (PMID 25531318, 2015). "Aberrant mTOR pathway activation has been reported in different cancers including hematologic malignancies by different mechanisms." (PMID 25682198, 2015). "The PI3K-Akt-mTOR pathway controls several aspects of cancer cells including, growth, proliferation, cell cycle, motility, genomic instability and metabolism." (PMID 26046375, 2015). "Dysregulation of mTOR signaling in cancer has been observed to result from both aberrant upstream and downstream signaling pathways." (PMID 25849580, 2015). "To elucidate the signaling pathway involved in the AFP modulation, we assessed the role of the two most activated signaling pathways in cancer cells: the PI3k/Akt/mTOR and the MAPK/ERK pathways." (PMID 25822740, 2015). "Following reports on several anticancer agents inhibiting mTOR signaling and induce autophagy in cancer cells by suppressing major components in the mTOR axis." (PMID 26098947, 2015). "Energy starvation of cancer cells not only downregulates the mTOR pathway, but also likely inhibits fatty acid synthesis and perturbs redox balance, leading to broad changes in cellular metabolism." (PMID 26313261, 2015). "The contribution of the phophatidylinositide-3-kinase (PI3K)/Akt/mammalian target of rapamycin (mTOR) axis to survivin expression is observed not only in various cancer cells, but also in normal cells including cardiac myocytes." (PMID 26271039, 2015). "Previous study has reported that targeting PI3KCI/Akt/mTOR signaling with inhibitors such as ATP-competitive compounds can improve cancer therapeutic effect because the catalytic sites of PI3KCI and mTOR share a high degree of sequence homology." (PMID 25797270, 2015). "In cancer cells, oncogene activation leads to elevated mTOR activity, promoting survival and biosynthetic processes necessary for cell division." (PMID 25576920, 2015). "The PI3K/Akt/mTOR pathway, an intracellular signalling network that is often constitutively hyperactivated in many types of cancer and is known to have prototypic functions in cellular proliferation, growth, differentiation and survival." (PMID 26436418, 2015). "In cancers, EMT is associated with resistance to chemotherapeutic drugs and radiation, via activation of the PI3K/Akt/mTOR pathway." (PMID 26517240, 2015). "NVP-BEZ-235 has been shown to inhibit both PI3K/Akt and mTOR signaling and inhibits tumor growth in various cancers and is undergoing in phase I/II clinical trials for use in solid tumors." (PMID 26451606, 2015). "As indicated by the densitometric analysis, BKM120 exposure dose-dependently reduced the phospho/total protein ratios of critical PI3K/Akt/mTOR pathway components, emphasizing once again the selective target inhibition prompted by this drug on cancer cells." (PMID 26674543, 2015).
cancer (continued). "MAPK activation accompanied with incomplete inhibition of S6 phosphorylation and Akt activation indicated resistance to rapamycin, and provided rationale for a combination of MAPK and mTOR inhibitors in treatment of cancer." (PMID 25944619, 2015). "mTOR has been an attractive target for cancer in general, with hematologic malignancies in particular." (PMID 25859554, 2015). "Dysregulation in the PI3K/AKT/mTOR pathway also prove to be critical in MDR modulation in various cancers." (PMID 26098947, 2015). "Molecular mechanisms accounting for biguanide-mediated potentiation of targeted inhibitors likely include pleiotropic effects from altering cancer cell metabolism and inhibition of the mammalian target of rapamycin (mTOR) molecule." (PMID 26000092, 2015). "Recently, preliminary clinical data have indicated a certain antitumor activity of the mTOR inhibitor Rapamycin and its analogues in some cancers including NSCLC." (PMID 26061184, 2015). "PI3K/Akt/mTOR signaling pathway contributes, partially, to the cancer cell killing effect of Danu in C13 and A2780cp cells." (PMID 26580601, 2015). "Pathway analysis predicted that the MIC/CSCCs were enriched with cancer-related signalings such as cell adhesion, mTOR signaling pathway and cell migration that were depleted in the CINs." (PMID 25738363, 2015). "Considering SLC2A1 as a key rate-limiting factor for aerobic glycolysis in cancer cells, we next evaluated the effect of the MTOR signal cascade on aerobic glycolysis in HuH-7 cells." (PMID 25909713, 2015). "This intracellular re-localization of mTOR by treatment with extracellular protein highlights the importance of macropinocytosis and autophagic degradation for cancer growth and survival." (PMID 26575954, 2015). "The PI3K/Akt signaling pathway is activated in numerous cancers and plays important roles in tumor progression by phosphorylating various substrates such as mTOR, BCL-2, FoxO-family transcription factors, among others." (PMID 25714026, 2015). "Intuitively, most of the mutations reported in various cancer genome databases cluster in key regulatory domains, such as the FRB and kinase domains of mTOR." (PMID 26255626, 2015). "Overactivation of the PI3K-Akt-mTOR pathway has been reported in various human cancers, including RCC." (PMID 25784113, 2015). "More importantly, targeting mTOR with small-molecule inhibitors has exhibited antitumor activity for malignant tumor in clinical trials." (PMID 26259252, 2015). "Nonetheless, there were some contradictory reports that inhibition of the PI3K-Akt-mTOR signaling pathway induced autophagy in cancer cells." (PMID 26666173, 2015). "Since there is currently no drug that can directly inhibit the deregulated eIF4F complex in cancer cells, we assessed the effect of the next generation dual mTOR inhibitor CC214-1 on the translation initiation complex downstream of mTOR." (PMID 25839159, 2015). "It is determined that Akt/mTOR/S6 pathway is involved in cell proliferation and apoptosis of cancer cells." (PMID 26633375, 2015). "Increasing evidence implicates that mTOR pathway also plays a crucial role in the regulation of tumor cell motility and invasion, as well as cancer metastasis." (PMID 25762619, 2015). "The drug ability to inhibit cancer growth has been often correlated to the inhibition of the proliferative processes controlled by the mTOR pathway." (PMID 26291325, 2015). "Determination of the role of klotho, progerin and mTOR in colonic carcinogenesis will be a fundamental advance in our understanding of cancer as part of the human ageing process." (PMID 25388238, 2015). "Recent report shows the correlation between autophagy and the resistance of cancer cells to aspirin-induced apoptosis, aspirin induces protective autophagy, a feature of mTOR inhibition." (PMID 25388762, 2015). "Aberrant activation of mTOR signaling is frequently observed in many types of cancers, implicating its cancer promoting role." (PMID 25749387, 2015).
cancer (continued). "For example, Matsumoto and colleagues found that inhibiting mTOR signaling upregulates CD133 expression in a CD133-overexpressing cancer cell line." (PMID 26202311, 2015). "EGFR signaling is one of the major upstream regulators of mTOR, and its activation induces resistance to crizotinib as well as cancer stemness." (PMID 26517679, 2015). "It has a similarly large interactome in HEK293 cells (unpublished data) but, in the cancer interactome, although TOP mRNAs are present, there is a preponderance of cancer-sustaining transcripts including mTOR and other components of its signalling pathway." (PMID 26501340, 2015). "To our surprise, we did not detect any change in the phosphorylation of TSC2, ACC, or mTOR in H1299, A549, and H322 cancer cells after inducing PKR." (PMID 25798539, 2015). "Rapamycin revealed the mammalian target of rapamycin (mTOR) signaling pathway, which is important for normal cell and cancer cell growth." (PMID 28943624, 2015). "Rapamycin markedly prolonged lifespan and healthspan in cancer‐ and infection‐prone mice supporting disease mitigation as a mechanism for mTOR suppression‐mediated longevity extension." (PMID 26315673, 2015). "Most importantly, mTOR centrally modulates proliferative signal transduction, it was nominated as the ideal target for cancer treatment." (PMID 26107953, 2015). "Several other studies have also reported that HDACIs can inhibit the PI3K/AKT/mTOR signaling pathway in cancer cells." (PMID 26287365, 2015). "The PI3K/Akt pathway directs cancer cells towards aerobic glycolysis by activating the c-Myc and mTOR pathways." (PMID 26244812, 2015). "The aberrant expressions of PI3K/AKT/MTOR are found in several tumor types and are important to the initiation and progression of cancers." (PMID 26284195, 2015). "For example, some clinical approaches to lower autophagic activity in cancer cells target the mTOR and PI3K complexes." (PMID 26158518, 2015). "Together, these studies demonstrate that mTOR signaling plays a critical role in regulating the activity and function of HSPCs, suggesting that hematopoietic toxicity would be a concern for the application of mTOR inhibitors in cancer treatment." (PMID 26221145, 2015). "This was especially noted for growth-promoting pathways including the Insulin, mTOR, ErbB, Wnt, MAPK, and VEGF signaling pathways, and various cancer-associated pathways." (PMID 25960543, 2015). "The focus of the present study is to elucidate the role of mTOR-mediated metabolic reprogramming and its consequences in proliferation and survival of human cancer cells." (PMID 27551450, 2015). "Here we found that inhibition of mTOR by rapamycin reduced the basal or type I insulin-like growth factor (IGF-1)-stimulated adhesion of cancer cells." (PMID 25762619, 2015). "Mammalian target of rapamycin (mTOR) is also a serine/threonine protein kinase, modulating cancer cell proliferation, mortality, survival and protein synthesis." (PMID 26421002, 2015). "In many cancer cells, mTOR is highly expressed leading to the induction of several proteins that regulate aerobic glycolysis in cancer cells." (PMID 25807077, 2015). "Inhibition of PI3K/AKT/mTOR pathways has been evaluated as a potential strategy to sensitize tumor cells to radiation in different cancer cell lines, however the inhibitors that are currently available are effective in only relatively high concentrations." (PMID 26517240, 2015). "mTOR is a critical target for controlling cell cycle progression, senescence and cell death in mammalian cancer cells." (PMID 26636543, 2015). "In fact, mTOR signaling mediated translational control of protein synthesis and high activity of mTOR signaling in cancer cells was found in different types of cancer cells." (PMID 25821829, 2015).
cancer (continued). "Many studies have reported that the mTOR signaling pathway plays a significant role in maintaining cancer cell growth dysfunction and migration; therefore, we investigated the role that mTOR signaling played in NPC CSCs." (PMID 26202311, 2015). "Combination of PI3K inhibitors and mTOR inhibitors, dual mTORC1/2 inhibition, and mTOR and receptor tyrosine kinase inhibitors are strategies being explored for cancers of endocrine tissues in which the PI3K/Akt/mTOR pathway is hyperactivated." (PMID 26793165, 2015). "The mammalian target of rapamycin (mTOR) is dysregulated in diverse cancers and contributes to tumor progression and drug resistance." (PMID 25654224, 2015). "This pathway is all the more interesting that it is known to regulate Mcl-1 translation and is targeted in this way to sensitize several types of cancer justifying the development of pharmacological PI3K/AKT/mTOR inhibitors." (PMID 25627260, 2015). "Metformin is proposed as adjuvant therapy in cancer treatment because of its ability to limit cancer incidence by negatively modulating the PI3K/AKT/mTOR pathway." (PMID 26291325, 2015). "Our data provides new clues on the relationship among complex I deficiency, the Akt/mTOR pathway, EMT and cancer metastasis." (PMID 26641458, 2015). "Recently, mTOR inhibitor rapamycin was reported as a pharmacological inhibitor of lactate generation in cancer cells." (PMID 25938544, 2015). "The mTOR-pathway controls cell survival and cell growth and is involved in multiple cancers and has been actively investigated as a target for cancer therapies." (PMID 25945839, 2015). "Although clinical results have been obtained with three prototypes of mTOR inhibitors, all rapamycin-analogs, clinical updates unfortunately indicate that rapamycin shows promising results against only few types of cancer." (PMID 26536660, 2015). "The central importance of this pathway for cancer biology is reflected by the fact that an mTOR inhibitor, sirolimus (also known as rapamycin), is already in use in oncology practice, and several trials of PI3K and AKT inhibitors are underway." (PMID 26245297, 2015). "The PI3K/AKT/mTOR pathway, serving as a proto-oncogenic pathway, has been critical for cancer progression, including cellular proliferation, growth, survival, and drug resistance." (PMID 26325371, 2015). "It is interesting that mTOR-stimulated SESN2 activation modulates PTEN, and both mutant PTEN and overactivated mTOR are commonly found in human cancers." (PMID 25792980, 2015). "The SDF-1α/CXCR4 biological axis can activate multiple intracellular signaling pathways, including the FAK, AKT, ERK1/2, P38, STAT3, mTOR, and Wnt/β-catenin signaling pathways in various cancers." (PMID 25609203, 2015). "We found that along with KLF4 suppression, p110δ, a catalytic subunit of PI3K in cancer, Akt and mTOR (another identified target of miR-7) were significantly down-regulated in PC3-miR-7 cells and its derived xenografts." (PMID 26172296, 2015). "The mTOR pathway is commonly deregulated in several types of human cancers and its activity is regulated in response to the availability of growth factors and nutrients in the extracellular milieu." (PMID 26046375, 2015). "Increasing evidence has shown that mTOR signaling is activated in cancer cells and CSCs, which regulate proliferation, self-renewal and survival." (PMID 26202311, 2015). "Given the potential power of mTOR signaling with regard to cellular processes, the pathway has been an attractive therapeutic target for various maladies including cancer, type II diabetes, obesity and neurodegeneration." (PMID 25849580, 2015).